SPATA13 (spermatogenesis associated 13 )
Gene: Long non-coding RNA gene on chromosome 13 (23,979,810 to 24,035,027, forward strand). Ensembl gene ENSG00000228741.
Gene-disease validity (ClinGen):
ClinGen rates the evidence that SPATA13 causes each of these diseases.
primary angle-closure glaucoma (autosomal dominant): Limited. An angle-closure glaucoma characterized by closure of the anterior chamber angle by an intrinsic defect such that aqueous outflow is blocked and the intraocular pressure becomes inappropriately elevated leading to optic nerve damage and visual field loss.
Diseases named in the same sentence as SPATA13 in open-access papers:
SPATA13 is named in the same sentence as 19 diseases in open-access papers, as found by Europe PMC text mining. Sharing a sentence is not in itself a finding about the gene and the disease. The quoted sentences say what the papers report.
thyroid cancer (3 papers, 2018 to 2024). "It is noteworthy that the last study showed novel loci containing genes that were previously implicated in thyroid cancer (e.g., HES1, SPATA13, DIRC3, ID4) and a positive association of TSH with VEGFA expression, therefore angiogenesis." (PMID 39767631, 2024). "Importantly, this was the first study to identify SPATA13 as a gene that was associated with both PACG and any eye disease, though GWAS have implicated the gene product (protein SP-1277) with other disorders such as anorexia nervosa, thyroid cancer, and intellectual disability." (PMID 33396423, 2020).
alcohol dependence (2 papers, 2017 to 2019). Physical and psychological dependence on alcohol. "Prior GWAS has shown that variants in SPATA13 are associated with psychological disorders, such as depression and alcohol dependence." (PMID 28820441, 2017).
colorectal tumor (2 papers, 2020 to 2024). "Our method introduced SPATA13 a guanine-factor as a novel amplification driver gene in colorectal carcinoma, required for MMP9 up-regulation via the JNK signaling pathway in colorectal tumor cells." (PMID 38195844, 2024).
Intellectual disability (2 papers, 2019 to 2020). "Within the brain Spata13 can modulate glutamatergic dendritic spine formation and evidence from human patients suggests that the gene is associated with intellectual disability." (PMID 31020388, 2019). "A recent study combining microarray and exome sequencing of patients with non-syndromic intellectual disability (ID) identified a missense mutation in SPATA13 in 16 patient families." (PMID 31020388, 2019). "While the potential mechanism by which this mutation may modulate the development of intellectual disability is unknown, it is notable that SPATA13 has been demonstrated to affect dendritic spine formation and that altered spine dynamics have been associated with ID and related symptoms." (PMID 31020388, 2019).
intestinal tumours (2 papers, 2019 to 2021). "Loss of Spata13, also known as the adenomatous polyposis coli exchange factor Asef2, has no identifiable phenotype although it has been shown to reduce the number and size of intestinal tumours in Apc (Min/+) mice." (PMID 31020388, 2019). "SPATA13 is a discrete region in the adult brain enriched in a guanylate exchange factor, and deletion of SPATA13 has been shown to reduce and shrink the number and size of intestinal tumours in Apc (Min/+) mice, but its study in lung cancer is rare." (PMID 34804921, 2021).
lung carcinoma (2 papers, 2021 to 2023). "Compared with normal tissues, the expression of ADM2, CLIC6, KIF20A, LAD1, MUC5B, and TNS4 was up-regulated, and the expression of ATG16L2, KCNK3, MAFF, NKD1, and SPATA13 was down-regulated in lung cancer tissues." (PMID 34804921, 2021).
primary angle-closure glaucoma (2 papers, 2020 to 2023). "For SPATA13 gene, it has been reported to be associated with primary angle-closure glaucoma pathogenesis, by regulating nucleotide exchange factors activity and affecting homeostasis in the mitosis in the retina, RPE, cornea and lens etc." (PMID 37696869, 2023).
Anxiety (1 paper, 2019). Intense feelings of nervousness, tension, or panic often arise in response to interpersonal stresses. "Other behavioural aspects such as fear conditioning, anxiety-like behaviour, working memory, and thermal and mechanical sensitivity were not affected by the KO of Spata13 despite the gene’s enriched expression in the central extended amygdala." (PMID 31020388, 2019).
psoriasis (1 paper, 2025). An autoimmune condition characterized by red, well-delineated plaques with silvery scales that are usually on the extensor surfaces and scalp. "A 2019 proteomic study identified SLFN5 among a set of new disease-associated proteins in psoriasis, alongside other markers (ATM, ZNF512, SPATA13, etc.)." (PMID 41328434, 2025).
cancer (2 papers, 2017 to 2024). A tumor composed of atypical neoplastic, often pleomorphic cells that invade other tissues. "However, the association between SPATA13 and tumor size or T stage in cancer has not yet been reported." (PMID 38893126, 2024). "However, the association between SPATA13 mutations and survival has not been reported in any cancer, including RCC." (PMID 38893126, 2024).
tumor (1 paper, 2024). "In the Korean-KIRP dataset, SPATA13 mutations were additionally associated with tumor size (p = 0.013) and T stage (p = 0.018)." (PMID 38893126, 2024).
SPATA13 also shares sentences with these, for which no sentence is quoted: depression (2 papers); anorexia nervosa (1); breast tumors (1); colorectal carcinoma (1); diabetes (1); hypothyroidism (1); neuropathies (1); Sepsis (1).